CHRNA3 (cholinergic receptor nicotinic alpha 3 subunit)
Description:
Component of neuronal acetylcholine receptors (nAChRs) that function as pentameric, ligand-gated cation channels with high calcium permeability among other activities. nAChRs are excitatory neurotrasnmitter receptors formed by a collection of nAChR subunits known to mediate synaptic transmission in the nervous system and the neuromuscular junction. Each nAchR subunit confers differential attributes to channel properties, including activation, deactivation and desensitization kinetics, pH sensitivity, cation permeability, and binding to allosteric modulators. CHRNA3 forms heteropentameric neuronal acetylcholine receptors with CHRNB2 and CHRNB4, with CHRNA5, and CHRNB3 as accesory subunits. CHRNA3:CHRNB4 being predominant in neurons of the autonomic ganglia, it is known as ganglionic nicotinic receptor. CHRNA3:CHRNB4 or CHRNA3:CHRNA5:CHRNB4 play also an important role in the habenulo-interpeduncular tract, modulating the mesolimbic dopamine system and affecting reward circuits and addiction (By similarity). Hypothalamic CHRNA3:CHRNB4 nAChR activation by nicotine leads to activation of POMC neurons and a decrease in food intake (By similarity). Also expressed in the urothelium where it modulates reflex bladder activity by increasing intracellular calcium through extracellular influx and basal ATP release (By similarity).
Synonyms: NACHRA3; BAIPRCK; LNCR2; PAOD2
Tractability: Small molecule: an approved drug acts on it; a structure with a bound ligand is known; a high-quality ligand is known; it belongs to a druggable protein family. Antibody: UniProt places it where antibodies can reach, with high confidence; its Gene Ontology location is reachable by antibodies, with high confidence; UniProt predicts a signal peptide or a membrane-spanning region. PROTAC: UniProt records ubiquitination sites on it; ubiquitination databases record sites on it; a small molecule that binds it is known. Other modalities: a drug acting on it is in phase 2 or 3 trials.
Target class: Ion channel; Nicotinic acetylcholine receptor alpha subunit; Ligand-gated ion channel; Nicotinic acetylcholine receptor
Safety:
Unwanted effects reported when the protein is acted on. In parentheses: how it was acted on, where the effect was seen, and who reports it.
lung function (source: ClinPGx)
nicotine addiction (source: ClinPGx)
nicotine dependence (source: ClinPGx)
smoking addiction (source: ClinPGx)
Substance-Related Disorders (source: ClinPGx)
successfully quit smoking (source: ClinPGx)
Gene: Protein-coding gene on chromosome 15 (78,593,052 to 78,621,295, reverse strand). Ensembl gene ENSG00000080644.
Subcellular location: Synaptic cell membrane; Cell membrane; Endoplasmic reticulum; Golgi apparatus
Subcellular location (Human Protein Atlas): Nuclear speckles; Plasma membrane; Basal body; Cytosol; Primary cilium tip; Primary cilium transition zone
Pathways (Reactome):
Neuronal System: Highly calcium permeable nicotinic acetylcholine receptors; Highly calcium permeable postsynaptic nicotinic acetylcholine receptors; Highly sodium permeable postsynaptic acetylcholine nicotinic receptors
Gene Ontology:
Molecular function: acetylcholine receptor activity; acetylcholine-gated monoatomic cation-selective channel activity; protein binding; acetylcholine binding; ligand-gated monoatomic ion channel activity; neurotransmitter receptor activity; extracellular ligand-gated monoatomic ion channel activity; monoatomic ion channel activity; transmembrane signaling receptor activity
Biological process: acetylcholine receptor signaling pathway; behavioral response to nicotine; nervous system development; regulation of appetite; signal transduction; synaptic transmission involved in micturition; calcium ion transport; excitatory postsynaptic potential; locomotory behavior; membrane depolarization; monoatomic ion transmembrane transport; monoatomic ion transport; neuromuscular synaptic transmission; presynaptic modulation of chemical synaptic transmission; regulation of acetylcholine secretion, neurotransmission; regulation of dendrite morphogenesis; regulation of membrane potential; regulation of smooth muscle contraction; response to acetylcholine; response to nicotine; synaptic transmission, cholinergic
Cellular component: acetylcholine-gated channel complex; plasma membrane; synapse; dendrite; endoplasmic reticulum; Golgi apparatus; membrane; neuron projection; neuronal cell body; plasma membrane raft; presynaptic membrane; synaptic membrane; postsynaptic membrane
Genetic constraint (gnomAD): Loss-of-function variants: 35 observed, 43.57 expected, observed/expected ratio (o/e) 0.8, 90% interval 0.61 to 1.07. The upper end of that interval is the gene's LOEUF score, 1.07, which puts it in group 4 of 6, group 1 being the genes least tolerant of losing a copy. Missense variants: 541 observed, 657.32 expected, observed/expected ratio (o/e) 0.82, 90% interval 0.77 to 0.88. Synonymous variants: 281 observed, 267.86 expected, observed/expected ratio (o/e) 1.05, 90% interval 0.95 to 1.16.
Homologues: Orthologues: chimpanzee CHRNA3 (99% identical), macaque CHRNA3 (97% identical), pig CHRNA3 (92% identical), guinea pig CHRNA3 (92% identical), mouse Chrna3 (90% identical), dog CHRNA3 (90% identical), rabbit CHRNA3 (90% identical), rat Chrna3 (89% identical), zebrafish chrna3 (73% identical), tropical clawed frog chrna3l (69% identical). Paralogues in human: CHRNA6 (63% identical), CHRNA4 (55% identical), CHRNA2 (54% identical), CHRNB4 (44% identical), CHRNA1 (44% identical), CHRNB2 (44% identical), CHRNB3 (44% identical), CHRNA5 (43% identical), CHRNA7 (36% identical), CHRND (35% identical), CHRNB1 (33% identical), CHRNE (32% identical), and 33 more.
Diseases named in the same sentence as CHRNA3 in open-access papers:
CHRNA3 is named in the same sentence as 66 diseases in open-access papers, as found by Europe PMC text mining. Sharing a sentence is not in itself a finding about the gene and the disease. The quoted sentences say what the papers report.
lung carcinoma (70 papers, 2009 to 2025). "Studies have shown that genetic variants in the α-nAChR 3/5 subunit locus (CHRNA3/5) can influence nicotine dependence, smoking behaviors, and lung cancer risk." (PMID 41007821, 2025). "Certain genes, such as CHRNA3/5, have been strongly linked to both lung cancer and smoking behaviors." (PMID 39449814, 2024). "Polymorphisms in CHRNA3 have been associated with increased smoking initiation risk and increases susceptibility to lung cancer." (PMID 31214250, 2019). "Among the selected genes and their reference SNPs, CHRNA3 rs1051730 was the most significantly associated with increased lung cancer risk." (PMID 30104567, 2018). "We also found and validated a significant dose–response relationship between the number of CHRNA3 rs1051730 T alleles and lung cancer risk (adjusted trend test P = 2.68 × 10−24 for discovery and adjusted trend test P = 1.82 × 10−44 for replication)." (PMID 30104567, 2018). "This one SNP was rs578776, on chromosome 15 in the 3' untranslated region of CHRNA3, in the chr.15q25 locus known to be associated with different histology subtypes of lung cancer." (PMID 29486777, 2018). "For the CHRNA3/5 region, we found associations with traits which associate with smoking behaviour: nicotine dependence, lung cancer, chronic obstructive pulmonary disease and schizophrenia." (PMID 29030599, 2017). "Both types of tumors also share a transcriptional dysregulation of the three nAChR subunit genes grouped at the chromosomal locus (15q25.1) that predisposes to lung cancer; gene expression was reduced (CHRNA3) or increased (CHRNA5 and CHRNB4)." (PMID 28978081, 2017). "After identifying the impact of chromosome 15q25.1 and CHRNA3 gene on the susceptibility of lung cancer by three GWAS in 20086, 7, 8, further GWAS and meta-analysis revealed many CHRNA3 polymorphisms relevant to lung cancer." (PMID 26831765, 2016). "In GWAS, a nicotine receptor locus (CHRNA3, previously associated with increased smoking and lung cancer) was associated with fathers' survival." (PMID 27015805, 2016). "In 2008 and 2009, a genomic variant which caused synonymous substitution in CHRNA3, rs1051730, was reported to be associated with lung cancer and lung adenocarcinoma in two independent GWASs, respectively." (PMID 26859295, 2016). "Particularly they have identified that rs6495309T>C considerably influenced the CHRNA3 promoter activity, leading to higher α3-nAChR protein level and an increased risk of lung cancer." (PMID 26981122, 2016). "Genome-wide association studies (GWAS) have identified two CHRNA3 polymorphisms (rs578776 and rs938682) associated with lung cancer risk." (PMID 26831765, 2016). "The authors of a genome-wide association study of individuals of European descent found that a common SNP in the CHRNA3 gene increases the risk of lung cancer by moderating smoking quantity and nicotine dependence." (PMID 25874685, 2015). "The significant mediation impact of smoking on the association between rs1051730 in CHRNA3 and lung related diseases [overall lung cancer and chronic obstructive pulmonary disease (COPD)] were reported previously." (PMID 25233467, 2014). "Overall, we found a significant association between CHRNA3 rs6495309 polymorphism and lung cancer risk for Chinese (OR = 1.24, 95%CI = 1.07–1.44, P = 0.005)." (PMID 25288178, 2014). "Via a comprehensive meta-analysis, we evaluated the association of one common polymorphism in the CHRNA3 gene with the risk of lung cancer for Chinese." (PMID 25288178, 2014). "As for the CHRNA3 gene, despite of the rs6495309 polymorphism, several polymorphisms were also investigated for the associations with lung cancer risk for Chinese, such as the rs8034191 and rs1051730." (PMID 25288178, 2014). "Several GWAS have demonstrated that genetic variants in CHRNA5 and CHRNA3, located at the 15q25.1 lung cancer susceptibility locus, influence the risk of developing lung cancer in European and US populations." (PMID 25329654, 2014).
lung carcinoma (continued). "Overall, we found a significant association between CHRNA3 rs6495309 polymorphism and lung cancer risk for Chinese (OR = 1.62, 95%CI = 1.32–2.00, P < 0.00001)." (PMID 25288178, 2014). "Overall, we found a significant association between CHRNA3 rs6495309 polymorphism and lung cancer risk for Chinese (OR = 1.47, 95%CI = 1.33–1.63, P < 0.00001)." (PMID 25288178, 2014). "This is, to our knowledge, the first meta-analysis that investigated the association between the CHRNA3 polymorphisms and lung cancer risk for Chinese." (PMID 25288178, 2014). "Additional studies with a greater number of patients should be performed to examine how the CHRNA3 variants interact with other risk loci to influence lung cancer risk." (PMID 25288178, 2014). "Overall, we found a significant association between CHRNA3 rs6495309 polymorphism and lung cancer risk for Chinese (OR = 1.26, 95%CI = 1.13–1.41, P < 0.0001)." (PMID 25288178, 2014). "This meta-analysis of five case-control studies suggested that CHRNA3 rs6495309 polymorphism is associated with an increased risk of lung cancer in Chinese." (PMID 25288178, 2014). "SNP rs1051730 in the CHRNA3 gene was strongly associated with lung cancer risk (p = 1.5×10−8) and cigarettes per day (P = 5×10−16)." (PMID 25233467, 2014). "CHRNA3 encodes nAChRs, which is present either in neurons or in lung epithelial cells and lung cancer cell lines." (PMID 24686516, 2014). "Overall, we found a significant association between CHRNA3 rs6495309 polymorphism and lung cancer risk for Chinese (OR = 1.42, 95%CI = 1.26–1.61, P < 0.00001)." (PMID 25288178, 2014). "Overall and subgroup analyses of CHRNA3 gene rs1051730 polymorphism with the odds of developing lung cancer under allelic and dominant models." (PMID 22701590, 2012). "Three recent GWA studies showed that SNPs in a region of chromosome 15q25 were significantly associated with lung cancer; several nicotinic acetylcholine receptor genes, including CHRNA3 and LOC123688, are located in this region." (PMID 22356581, 2012). "They found a functional SNP (rs6495309) in the CHRNA3 gene that exerted an effect on regulating gene expression, leading to an increased lung cancer risk." (PMID 23056235, 2012). "Many independent studies have replicated the finding of association of CHRNA3-CHRNA5-CHRNB4 on 15q24 with lung cancer and smoking behavior." (PMID 23094028, 2012). "SNPs in the chromosome 15 CHRNA3/CHRNA5/LOC123688/IREB2 region have been shown to have associations with lung cancer and COPD unrelated to AAT deficiency." (PMID 22356581, 2012). "In addition, multiple genes, including CHRNA3/5, were strongly associated with lung cancer, smoking behaviours, and nicotine addiction." (PMID 35194190, 2022). "But, CHRNA3 (OMIM#118503) polymorphisms were found to contribute to an increased risk of lung cancer in the Han individuals who smoke, however, CHRNA3 variant (rs8042374, NM_000743.4:g.78615690A>G) was linked to a greater risk of lung adenocarcinoma in female nonsmokers." (PMID 31342675, 2019). "Therefore, in this study we aimed at determining the frequency of the SNPs (rs16969968 in CHRNA5, and rs1051730 in CHRNA3) and elucidating their possible role in risk for nicotine dependence and lung cancer among the Palestinian population." (PMID 29609626, 2018). "However, the association between both CHRNA3 single nucleotide polymorphisms (SNP, rs578776, rs938682) and susceptibility of lung cancer remains inconsistent." (PMID 26831765, 2016). "Thus, a total of 5 articles that investigated the association between the rs6495309 polymorphism in CHRNA3 gene and the risk of lung cancer in Chinese were left for data extraction." (PMID 25288178, 2014). "Genome-wide association studies (GWAS) have identified that chromosome 15q25.1, composed of nicotinic acetylcholine receptor genes, including CHRNA5 and CHRNA3, are lung cancer susceptibility regions and play a potential role in multiple smoking-related phenotypes and nicotine dependence." (PMID 25329654, 2014).
lung carcinoma (continued). "Compared with the previous meta-analysis, we added another CHRNA3 polymorphism that might contribute lung cancer risk in Chinese using newly published studies." (PMID 25288178, 2014). "The pooled results indicated that there were obvious associations between CHRNA3 rs6495309 polymorphism and lung cancer in Chinese under all models: allele contrast (C vs. T), homozygote (CC vs. TT), heterozygote (CT vs. TT), dominant (CC + CT vs. CC) and recessive (TT vs. CT + CC) model." (PMID 25288178, 2014). "Our findings demonstrated that CHRNA3 gene rs6495309 polymorphism might be a risk factor for the development of lung cancer in Chinese." (PMID 25288178, 2014). "Future studies that include detailed information on exposures to various carcinogens and individual-level data to assess the possible gene-gene and gene-environment interactions in the association between CHRNA3 rs6495309 polymorphism and lung cancer risk are needed." (PMID 25288178, 2014). "The overall comparison of CHRNA3 gene rs1051730-A allele yielded a remarkably increased risk for lung cancer (OR = 1.33; 95% CI: 1.24–1.44; P<0.0005) relative to the rs1051730-G allele; however, there was moderate evidence of between-study heterogeneity (I2 = 57.8%; P = 0.003)." (PMID 22701590, 2012). "CHRNA3 was associated with lung cancer in three separate large GWA studies." (PMID 22356581, 2012). "CHRNA3/5 is the same locus that has been implicated in the risk of lung cancer." (PMID 19300482, 2009). "This is similar to the recently reported association of CHRNA3/5 SNPs with lung cancer." (PMID 19300482, 2009). "Additionally when screening the published GWAS researches including CHRNA3 gene, we found another independent locus rs8040868 (C > T) might be related to risk of lung cancer." (PMID 26831765, 2016). "Moreover, there is controversy as to whether SNPs in the CHRNA3 gene have a direct carcinogenic effect on lung cancer risk or impact indirectly through smoking." (PMID 24686516, 2014). "Finally, this meta-analysis could not address the gene-gene and gene-environmental interactions in the association between CHRNA3 rs6495309 polymorphism and lung cancer risk." (PMID 25288178, 2014). "The association between the rs6495309 polymorphism in CHRNA3 gene and lung cancer risk has been studied in Chinese by several number case-control control studies with small number of cases and controls, and these studies might be underpowered to reveal the true association." (PMID 25288178, 2014). "Thus, the CHRNA3 rs6495309 polymorphism could be suggested as a lung cancer risk factor for Chinese." (PMID 25288178, 2014). "PheWAS confirmed chromosome 15 SNPs as jointly associated with respiratory traits and lung cancer, regulating IREB2, CHRNA3/5, HYKK, and PSMA4." (PMID 41377765, 2025). "Over the past decade, GWASs have identified multiple susceptibility loci associated with lung cancer risk, including TP63, TERT, CDKN2A/B and CHRNA3/5." (PMID 35194190, 2022). "The most common genes shared by these multimorbidities are IREB2 and CHRNA3, located in 15q25, a well-known region for association with COPD, lung cancer, and smoking." (PMID 34225788, 2021). "CHRNA3/B4 intergenic SNPs rs6495309, located on the promoter, has been associated with nicotine dependence, COPD and risk for lung cancer." (PMID 29416783, 2018). "Previously CHRNA3/CHRNA5/CHRNB4 locus and nearby gene PSMA4 have been associated with increased risk of lung cancer." (PMID 30543688, 2018). "CHRNA5/CHRNA3/CHRNB4 gene cluster is located on chromosome 15q25.1 and was reported to be associated with risk of lung cancer." (PMID 29416783, 2018). "The difference in CHRNA3 rs1051730 and CHRNB4 rs6495309 combination was associated with lung cancer risk in a dose-dependent fashion in discovery (adjusted trend test P = 1.55 × 10−24) and replication (adjusted trend test P = 4.80 × 10−50)." (PMID 30104567, 2018).